BRCA1 (BRCA1 DNA repair associated)
Diseases named in the same sentence as BRCA1 in open-access papers (continued):
Sharing a sentence is not in itself a finding about the gene and the disease.
cancer (continued). "Germline variants such as BRCA1/2 play an important role in tumorigenesis and clinical outcomes of cancer patients." (PMID 31701019, 2019). "A paradigm for DNA repair targeted therapy has emerged in cancers that exhibit mutations in BRCA1 or BRCA2 tumor suppressor genes, conferring a strong defect in homologous recombination, a major and error-free DSB repair pathway." (PMID 31921645, 2019). "Because loss-of-function variants of BRCA1 are associated with a significantly increased risk of cancer, frame shift and nonsense mutations, whose impact on the protein can be easily inferred from the genetic code, are classified as pathogenic alterations." (PMID 31013702, 2019). "Olaparib, Niraparib, Rucaparib, Talazoparib and Veliparib are FDA approved drugs for PARP1 inhibition in BRCA1 mutated cancers." (PMID 31856867, 2019). "Both DNA mutations and epigenetic silence can lead to the loss of function of BRCA1 which are associated with human cancer including breast." (PMID 31023256, 2019). "When using cytologicaly derived cancer cells DNA to detect BRCA1/2 mutation, both germline and somatic BRCA1/2 mutations are identified." (PMID 30940100, 2019). "Efforts to expand the use of PARPis beyond cancers with BRCAness have identified cancer-associated molecular alterations other than BRCA1/2 that generate PARPi sensitivity in cancer." (PMID 31266951, 2019). "This is a report of 22 families with the same mutation, BRCA1 duplication exon 13, a mutation that is found world-wide, with the objective to describe the cancer history found in these families." (PMID 30136106, 2019). "Cancer associated mutations impaired the transcription activation assay while neutral mutations displayed the activity equivalent to the wild-type BRCA1." (PMID 31998812, 2019). "The identification of individuals harboring BRCA1/2 mutations is crucial to assess their cancer risk, consider preventive measures and tailor cancer management strategies." (PMID 31528241, 2019). "The cancer risks for patients with one of the three germline founder mutations in BRCA1 and BRCA2 have been extensively described." (PMID 30915162, 2019). "BRCA1 c.5266dupC mutation carriers demonstrated significantly shorter time of cancer development compared to patients carrying c.181T > G and c.4035delA mutations." (PMID 30918533, 2019). "Similar to BRCA1-mutated cancers, BRCA1-like cancers are aggressive and typically exhibit poor prognosis." (PMID 30683142, 2019). "To corroborate the findings from primary HMECs, we used MCF10A cells that were genetically engineered to harbor a single allele of cancer-causing BRCA1 mutation." (PMID 30995943, 2019). "A 2014 multicenter, open-label, noncomparative phase II clinical trial examined the efficacy of olaparib monotherapy in patients with advanced, recurrent cancer with a germline BRCA1/2 mutation." (PMID 30934991, 2019). "The mechanisms by which hormones promote cancer development in BRCA1 mutation carriers remain to be investigated." (PMID 31771627, 2019). "TNBC cancer cells exhibit several DNA repair pathway deficiencies, such as deleterious mutations on the BRCA1/2 genes or assimilated “BRCAness” phenotypes." (PMID 31888054, 2019). "For example, inhibitors of poly(ADP)‐ribose polymerase are effectively used to treat cancers that carry mutations in BRCA1 and/or BRCA2 and have shown promising results in CRC preclinical studies." (PMID 30714316, 2019). "Interventions, such as bilateral mastectomy, salpingo-oophorectomy or annual breast magnetic resonance imaging (MRI) screening, are offered to women carrying BRCA1/2 PVs in order to reduce cancer risk and to consent early detection." (PMID 31336956, 2019).
cancer (continued). "To date, stabilization of stalled DNA replication forks was a recently identified PARPi-resistance mechanism that promotes genomic stability in BRCA1/2-deficient cancers." (PMID 31803609, 2019). "Discussion and conclusion: Carriers of the most frequent Norwegian path_BRCA1 variants had low incidence of cancer in fertile ages, indicating a low selective disadvantage." (PMID 30678073, 2019). "The risk and prevalence of specific germline variants in cancer predisposition genes greatly vary across ethnicities and cancer types, as illustrated by the high prevalence of BRCA1 and BRCA2 variants in Ashkenazi Jews." (PMID 31391007, 2019). "Approximately 28% of variant-positive individuals had a personal history, and 45% had a personal or family history of BRCA1/2-associated cancers." (PMID 31892343, 2019). "As with previous studies, there was a higher rate of relevant cancers in BRCA1 variant-positive individuals than in BRCA2, and in women than in men." (PMID 31892343, 2019). "Specific agents, such as platinum compounds or poly (ADP-ribose) polymerase (PARP) inhibitors, are effective treatments for some cancers involving BRCA1 or BRCA2 mutation." (PMID 31666926, 2019). "Based on synthetic lethal theory, Poly (ADP-ribose) polymerase inhibitor (PARPi) was developed aiming to selectively target cancer cells harboring BRCA1/2 mutations." (PMID 31737426, 2019). "Several environmental factors such as birth cohort, age at menarche, number of pregnancies, therapeutic abortion, oral contraceptives, and prophylactic oophorectomy are suspected to affect the risk of cancer in BRCA1/2 mutation carriers." (PMID 31395037, 2019). "Combining studies of clinical samples and gene editing-generated isogenic cell lines, our work clearly demonstrates that a single copy of cancer-predisposing BRCA1 mutation reduces super-enhancer mark and enhancer function in transcriptional activation." (PMID 30995943, 2019). "Our results suggest that the clinical use of chlorambucil in the BRCA1/2‐deficient subset of cancer patients should be re‐evaluated." (PMID 31273933, 2019). "Mutations in BRCA1 and other DNA repair genes are common cause of cancer but deficient HR can be also exploited as target for cancer therapy." (PMID 31619012, 2019). "In this work, we have used both germline and somatic engineering approaches to rapidly test candidate cancer drivers in the WB1P mouse model of BRCA1-deficient TNBC." (PMID 30674894, 2019). "Bioinformatics analysis indicates that heterozygous cancer-predisposing BRCA1 mutation (BRCA1mut/+) dampens super-enhancer marks in primary human mammary epithelial cells (HMECs), in particular at those super-enhancers with GATA transcription factor binding." (PMID 30995943, 2019). "The assay was further validated by the functional impact of known cancer-associated variants and BRCA1 TA." (PMID 31013702, 2019). "PARP-1 inhibitors can be utilized not only as a single agent for the treatment of BRCA1- or BRCA2-deficient cancers, but in combination with DNA-damaging therapeutics (radiation or chemotherapy) to improve their potencies by blocking DNA-repairing process." (PMID 30427217, 2019). "The majority of TNBC patients carry mutations in the highly penetrant cancer susceptibility genes BRCA1 and BRCA2." (PMID 31683572, 2019). "Genomic analyses show the distinct molecular patterning of BRCA1-mutated, HR-deficient cancers compared to BRCA2-mutated amd HR-proficient cancers." (PMID 30683142, 2019). "Library preparation includes a so called tagmentation step in which high-quality, blood-derived DNA is sheared by a transposase and a capture step enriching 94 cancer-associated genes including BRCA1/2." (PMID 31029168, 2019). "Another study described a transfer of malignant traits to BRCA1 deficient human fibroblast when treated with either cancer patient sera or isolated cancer cell exosomes, leading to malignant transformation." (PMID 31134894, 2019).
cancer (continued). "In conclusion, we have demonstrated the role of family history of cancer in women diagnosed with OC for assessing the likelihood of a germline BRCA1 or 2 mutations status." (PMID 30821131, 2019). "In our cohort, 16 of 184 patients (9%; 95% CI 5%‐14%) with deleterious BRCA1 or 2 mutation would have been missed if they were tested based on the presence of family history of cancer." (PMID 30821131, 2019). "BRCA1/2 reversion mutations were found in pre-treatment ctDNA from eight patients: 2/11 (18%) of platinum-refractory cancers, 5/38 (13%) of platinum-resistant cancers, and 1/48 (2%) of platinum-sensitive cases." (PMID 31167492, 2019). "BRCA1-mutated cancers exhibit deficient homologous recombination (HR) DNA repair, resulting in extensive copy number alterations and genome instability." (PMID 30683142, 2019). "We decided to examine cancer incidence in fertile ages for the frequent path_BRCA1 variants in Norway based on the methods developed for estimating cancer incidences in the Prospective Lynch Syndrome Database (PLSD)." (PMID 30678073, 2019). "The c.5266dupC BRCA1 mutation was most frequent among patients who developed any cancer – 68.75% (11/16), followed by c.181T > G mutation – 25% (4/16), and c.4035delA observed in 6,25% (1/16) of patients." (PMID 30918533, 2019). "After a pathogenic BRCA1 mutation was found, the patient developed new anxieties as a result of the unexpected diagnosis and her history of the other type of cancer." (PMID 31263500, 2019). "HR-deficiency is, therefore, a driver of tumorigenesis as demonstrated in cancer cells deficient in BRCA1- and BRCA2 (BRCA) expression or functions." (PMID 31930278, 2019). "While mutations in BRCA1/2 are the most common alterations implicated in hereditary cancer syndromes, mutations in other genes are identified increasingly in cancer patients with the development of multigene panel testing." (PMID 31767017, 2019). "Genomic screening for pathogenic BRCA1/2 variants in apparently healthy individuals has the potential to lead to earlier diagnosis of cancer via increased surveillance, as well as cancer risk reduction via prophylactic medical interventions." (PMID 31892343, 2019). "The frequency of particular BRCA1 mutations observed between carriers who were diagnosed with any cancer reflects the frequency of these mutations in the Polish population." (PMID 30918533, 2019). "The present study used next-generation sequencing (NGS) technology to determine the prevalence of germline BRCA1/2 variants in a small cohort of breast/ovarian Italian cancer patients." (PMID 31336956, 2019). "PARPi are currently FDA approved for metastatic breast, ovarian and related cancers, mainly in patients with pathogenic variants in the BRCA1 & BRCA2 genes." (PMID 31159747, 2019). "Subsequent studies demonstrated that homologous recombination (HR) repair deficiencies can be exploited to selectively kill BRCA1/2-deficient cancer cells with G4 ligands." (PMID 31287417, 2019). "A recent study observed that cancer cells carrying mutations that lead to expression of a truncated BRCA1 protein, which maintained the ability to interact with PALB2, still developed PARPi resistance even in the absence of 53BP1." (PMID 30714316, 2019). "Initially, synthetic lethality concept development was encouraged to kill cancer cells with inactivating mutations in BRCA1 and BRAC2 by poly adenosine 5′-disphosphate ribose polymerase (PARP) inhibition." (PMID 31652722, 2019). "Based on this synthetic lethal effect, numerous PARPis are developed including Veliparib, Rucaparib, Olaparib, Niraparib, and Talazoparib, which are mainly applied in cancer patients with BRCA1/2 mutations." (PMID 31521196, 2019). "It was demonstrated in the literature reports that the 135G/C and Q356R polymorphisms of RAD51 and BRCA1 genes, respectively, were associated with an increased risk of cancer and influenced the histological malignancy grading." (PMID 30712190, 2019).
cancer (continued). "Intriguingly, in specimens with BRCA1 mutations known to predispose for cancer, higher frequencies of lobular vDP cells are observed." (PMID 31619692, 2019). "It has previously been shown that if a BRCA1 variant cannot repair damaged DNA, then it is likely to cause cancer." (PMID 30925164, 2019). "It is therefore possible that the increased cytotoxicity of entinostat observed in BRCA1 mutated cancer cells was caused by the impairment in the DNA damage response in addition to the homologous recombination deficiency caused by BRCA1 loss of function." (PMID 31840082, 2019). "Identification of BRCA1 gene mutation makes a great value in cancer prognosis, treatment and early risk prediction." (PMID 31759379, 2019). "Several research groups point to increased replication fork stability as a contributor to PARPi resistance in BRCA1/2-deficient cancers." (PMID 30934991, 2019). "Secondly, we detected an augmented baseline IFN-γ signature in BRCA1-mutated cancer and primary epithelial cells and tumors coupled with decreased cytotoxicity induced by IFN-γ or by STAT1 knockdown." (PMID 31840082, 2019). "These numbers are in line with recently reported international trends in the uptake of cancer screening among BRCA1/2 mutation carriers." (PMID 31302855, 2019). "Somatic loss of 53BP1 expression in BRCA1‐mutated cancers leads to partial restoration of HR‐mediated DSB repair and contributed to resistance to PARPi." (PMID 30714316, 2019). "By contrast, larger indels (≥3 bp in motif size) were noted to be enriched in cancers with mutations in BRCA1/BRCA2." (PMID 30982602, 2019). "Some authors argue that these cancers are notlinked to BRCA1 germline mutations, but most likely constitutesporadic ER-positive tumors (Tung etal., 2010)." (PMID 31067289, 2019). "In order to minimise the risk of cancer incidence and mortality in women with a BRCA1 or BRCA2 mutation, uptake of both breast MRI and BSO should approach 100%." (PMID 30971774, 2019). "Collectively, our findings lend support to the notion that heterozygous BRCA1 mutations are haploinsufficient for transcriptional regulation in non-tumorigenic breast epithelial cells prior to clinically evident cancer appearance." (PMID 30995943, 2019). "Several mutations seen in different cancers lie on the dimerization interface, such as C61G on BRCA1, abolishing the ubiquitin ligase activity." (PMID 31803618, 2019). "We confirmed that cancer EVs contain genomic DNA spanning all human chromosomes and we observed that several mutated cancer genes were transferred to target BRCA1-KO fibroblasts." (PMID 31200749, 2019). "The HR activities of BRCA1 variants determined by this assay were better correlated with sensitivity to anti-cancer agents than those estimated by the DR-GFP assay." (PMID 30733539, 2019). "Cancer affecting breast, ovary, skin (SC), endometrium (EC), pancreas (PC) and prostate (PrC) accounted for 91.2% of all tumors registered in BRCA1/2 patients and 93.7% among HR-BRCA-negative and low risk cases." (PMID 31771539, 2019). "Cancer cells with deleterious BRCA1/2 mutations are defective in HRR and therefore are hypersensitive to PARP inhibitors." (PMID 30717758, 2019). "In a clinical setting, the identification of BRCA1 or BRCA2 mutations has gained significance as a tool for the implementation of cancer risk-reducing strategies." (PMID 30980249, 2019). "Alterations in splice site usage or selection have been shown to affect genes implicated in cancer susceptibility (BRCA1) and in tumor development or progression (e.g., MDM2, CD44)." (PMID 31683936, 2019). "Of the IFN-γ-related genes, IFI16 was upregulated >150-fold at baseline in BRCA1-mutated cancer cells." (PMID 31840082, 2019). "A major gap of knowledge in BRCA1-related cancer biology concerns the mechanism by which a single copy of BRCA1 mutant allele leads to luminal differentiation deficiency and eventually basal-like tumors." (PMID 30995943, 2019).
cancer (continued). "More important, we demonstrated that BRCA1-mutated fibroblasts turned into cancer cells, which exhibited phenotypical and immunohistochemical differentiation comparable to the cancer of the donor patients." (PMID 30787346, 2019). "Of note, targeting mortalin and PARP1 by Mortaparib also caused decrease in BRCA1 that has earlier been shown to cause collateral lethality of cancer cells and increase in γH2AX protein." (PMID 31856867, 2019). "Poly(ADP‐ribose) polymerase (PARP) inhibitors are selectively cytotoxic in cancer cells with defects in homologous recombination (HR) (e.g., due to BRCA1/2 mutations)." (PMID 31529615, 2019). "Oxidation of the gold nanoparticle modifications of the reporter probe were used for the specific detection of the BRCA1 gene associated with cancer." (PMID 31816919, 2019). "PARP inhibitors have shown great promise in clinical trials and are likely to come into general use in HR-deficient (and in particular BRCA1/2 loss of function) cancers." (PMID 31080552, 2019). "Both lobular DP cells from BRCA1 mutation carriers and cancer associated DP were generally CD146neg and as such similar to age related lobular vDP cells." (PMID 31619692, 2019). "The poly (adenosine diphosphate (ADP)-ribosyl) polymerase inhibitors (PARPi) selectively kill cancer cells with BRCA1 or BRCA2 (BRCA)-mutations." (PMID 31930278, 2019). "We observed that the time to any cancer diagnosis after RRSO was significantly shorter for c.5266dupC BRCA1 mutation carriers." (PMID 30918533, 2019). "The BRCA1/2 germline mutations can significantly increase the risk for breast, ovarian, and other cancers in women." (PMID 30968603, 2019). "Recently, homologous recombination repair of double-strand DNA breaks has attracted researcher focus as a target to develop an appropriate therapeutic strategy, e.g., PARP inhibitors for BRCA1/2-deficient cancers." (PMID 30975222, 2019). "Germline mutations in cancer-predisposing genes such as BRCA1/2 are also detected to assess cancer risk." (PMID 30671672, 2019). "Mosaic gene methylation as a cancer risk factor will be discussed further as part of reviewing BRCA1 methylation data below." (PMID 31225507, 2019). "The detection rate of BRCA1/2 mutations was higher in patients with three or more cancer family members than those with one or two." (PMID 30982232, 2019). "Genetic testing for BRCA1/2 mutations allows us to stratify families and individuals by their risk or predisposition to developing cancer, so that, preventive measurements can be offered to decrease cancer mortality and morbidity." (PMID 31771539, 2019). "Serum tumor markers and BRCA1/2 germline mutations are crucial factors in cancer diagnosis, treatment, and prognosis." (PMID 30972954, 2019). "It is often assumed any cancer in a germline BRCA1 or BRCA2 (collectively termed BRCA) mutation carrier was caused by that mutation." (PMID 31360904, 2019). "Until recently, relatively little is known about the predictive role of family history of cancer on the prevalence of germline BRCA1 or 2 mutations in OC patients." (PMID 30821131, 2019). "Cancers driven by loss of BRCA1/2 are associated with sensitivity to PARP inhibitors (PARPi), such as olaparib, through the synthetic-lethality of concomitantly blockading the single-strand repair pathways mediated by PARP." (PMID 31591445, 2019). "Study 42 is a clinical trial, which is used to assess the efficacy of oral Olaparib in patients with advanced cancer and who have a confirmed genetic BRCA1 and/or BRCA2 mutation." (PMID 31577767, 2019). "In agreement with studies from other countries, the combination of MRI and MMG was associated with a diagnosis of cancer at an earlier stage in women with a BRCA1 or BRCA2 mutation undergoing surveillance." (PMID 30980249, 2019).